ZNRF1 (zinc and ring finger 1)
Description:
E3 ubiquitin-protein ligase that plays a role in different processes including cell differentiation, receptor recycling or regulation of inflammation. Mediates the ubiquitination of AKT1 and GLUL, thereby playing a role in neuron cells differentiation. Plays a role in the establishment and maintenance of neuronal transmission and plasticity. Regulates Schwann cells differentiation by mediating ubiquitination of GLUL. Promotes neurodegeneration by mediating 'Lys-48'-linked polyubiquitination and subsequent degradation of AKT1 in axons: degradation of AKT1 prevents AKT1-mediated phosphorylation of GSK3B, leading to GSK3B activation and phosphorylation of DPYSL2/CRMP2 followed by destabilization of microtubule assembly in axons. Ubiquitinates the Na(+)/K(+) ATPase alpha-1 subunit/ATP1A1 and thereby influences its endocytosis and/or degradation. Controls ligand-induced EGFR signaling via mediating receptor ubiquitination and recruitment of the ESCRT machinery. Acts as a negative feedback mechanism controlling TLR3 trafficking by mediating TLR3 'Lys-63'-linked polyubiquitination to reduce type I IFN production. Modulates inflammation by promoting caveolin-1/CAV1 ubiquitination and degradation to regulate TLR4-activated immune response.
Synonyms: NIN283; FLJ14846; DKFZp434E229
Tractability: Antibody: UniProt places it where antibodies can reach, with high confidence. PROTAC: UniProt records ubiquitination sites on it; ubiquitination databases record sites on it; its protein half-life has been measured.
Gene: Protein-coding gene on chromosome 16 (74,999,014 to 75,110,994, forward strand). Ensembl gene ENSG00000186187.
Subcellular location: Endosome; Lysosome; Membrane; Cytoplasmic vesicle, secretory vesicle, synaptic vesicle membrane
Subcellular location (Human Protein Atlas): Vesicles; Primary cilium tip; Primary cilium transition zone
Pathways (Reactome):
Immune System: Antigen processing: Ubiquitination & Proteasome degradation
Gene Ontology:
Molecular function: protein binding; ubiquitin protein ligase activity; ubiquitin-protein transferase activity
Biological process: positive regulation of autophagosome-lysosome fusion; positive regulation of toll-like receptor 4 signaling pathway; proteasome-mediated ubiquitin-dependent protein catabolic process; protein K48-linked ubiquitination; protein ubiquitination
Cellular component: cytoplasm; cytosol; endosome; membrane; plasma membrane; lysosome; synaptic vesicle membrane
Genetic constraint (gnomAD): Loss-of-function variants: 3 observed, 15.56 expected, observed/expected ratio (o/e) 0.19, 90% interval 0.087 to 0.5. The synonymous counts are far from expectation, so gnomAD's model fits this gene poorly and the ratio says little. Missense variants: 310 observed, 270.14 expected, observed/expected ratio (o/e) 1.15, 90% interval 1.04 to 1.26. Synonymous variants: 157 observed, 115.85 expected, observed/expected ratio (o/e) 1.36, 90% interval 1.19 to 1.55.
Homologues: Orthologues: chimpanzee ZNRF1 (100% identical), dog ZNRF1 (99% identical), guinea pig ZNRF1 (99% identical), macaque ZNRF1 (99% identical), mouse Znrf1 (99% identical), rabbit ZNRF1 (99% identical), rat Znrf1 (99% identical), pig ZNRF1 (93% identical), zebrafish znrf1 (82% identical), tropical clawed frog znrf1 (70% identical). Paralogues in human: ZNRF2 (48% identical), RNF11 (20% identical).
Diseases named in the same sentence as ZNRF1 in open-access papers:
ZNRF1 is named in the same sentence as 22 diseases in open-access papers, as found by Europe PMC text mining. Sharing a sentence is not in itself a finding about the gene and the disease. The quoted sentences say what the papers report.
B-cell acute lymphoblastic leukemia (1 paper, 2019). A neoplasm of lymphoblasts committed to the B-cell lineage, typically composed of small to medium-sized blast cells. "Deletion of ZNRF1 may be involved in the mechanism of B-cell acute lymphoblastic leukemia associated with PAX5 alteration." (PMID 31417866, 2019).
cervical cancer (1 paper, 2021). A primary or metastatic malignant neoplasm involving the cervix. "Moreover, ZNRF1-mediated EGFR degradation was also observed in HeLa cervical cancer cells, indicating that ZNRF1 involvement in EGFR degradation is not limited to lung cancer cells." (PMID 33996800, 2021).
COVID-19 (1 paper, 2023). A disease caused by infection with severe acute respiratory syndrome coronavirus 2. "Interestingly, ZNRF1 expression in peripheral blood mononuclear cells was positively correlated with the severity of COVID-19." (PMID 37158982, 2023).
diabetes (1 paper, 2024). "Silencing Cav-1 and upregulating ZNRF1 were sufficient to improve EDR of diabetic aortas, while overexpression of Cav-1 and downregulation of ZNRF1 abolished the effects of NCEH1 on endothelial function in diabetes." (PMID 38664801, 2024).
diabetic retinopathy (1 paper, 2023). "It is known that rs17684886 in ZNRF1 is associated with diabetic retinopathy, and its expression is induced in peripheral nerves after injury, so its overexpression causes neurite-like elongation." (PMID 36975604, 2023).
endothelial dysfunction (1 paper, 2024). In vascular diseases, endothelial dysfunction is a systemic pathological state of the endothelium (the inner lining of blood vessels) and can be broadly defined as an imbalance between vasodilating and vasoconstricting substances produced by (or acting on) the endothelium. "Interestingly, knockdown of ZNRF1 weaken the protection of NCEH1 overexpression against endothelial dysfunction in HG-insulted mouse aortae ex vivo." (PMID 38664801, 2024).
glioblastoma (1 paper, 2023). The most malignant astrocytic tumor (WHO grade IV). "In glioblastoma (GBM), TRAF4 regulates caveolin 1 (CAV1) stability, and drives GBM cell stemness and temozolomide resistance by blocking ZNRF1-mediated ubiquitination and promoting USP7-mediated deubiquitination." (PMID 36765039, 2023).
kidney tumor (1 paper, 2023). "Our studies indicated that LZTFL1 inhibits kidney tumor cell proliferation by destabilizing AKT through ZNRF1-mediated ubiquitin proteosome pathway and inducing cell cycle arrest at G1." (PMID 36966254, 2023). "That being said, other mechanisms by which LZTFL1 inhibits kidney tumor cell proliferation may also be important as knockdown of ZNRF1 only partially reversed the effect of LZTFL1 on tumor cell growth." (PMID 36966254, 2023). "AKT is polyubiquitinated in the kidney tumor cells in the presence of ZNRF1." (PMID 36966254, 2023). "Our studies showed that ZNRF1 also targets AKT for degradation in kidney tumor cells." (PMID 36966254, 2023). "Mechanistically, we found that LZTFL1 inhibits kidney tumor cell cycle progression and suppresses the AKT signaling by destabilizing AKT via ZNRF1-mediated ubiquitin proteosome pathway (UPP)." (PMID 36966254, 2023). "Taken together, these results suggest that the effect of LZTFL1 on the AKT protein stability is mediated through ZNRF1, which is at least partially responsible for the anti-cell proliferative function of LZTFL1 on kidney tumor cells." (PMID 36966254, 2023).
leukemia (1 paper, 2022). A malignant (clonal) hematologic disorder, involving hematopoietic stem cells and characterized by the presence of primitive or atypical myeloid or lymphoid cells in the bone marrow and the blood. "PROM1, FLT3, CTGF, LGALS1, IGFBP7, ZNRF1, and RUNX2 were found highly expressed in the MLL-R pro-B ALL compared to the other subclassification of leukemia." (PMID 36276286, 2022).
myocarditis (1 paper, 2023). Myocarditis is a condition that is characterized by inflammation of the heart muscle (myocardium). "In addition, the serum levels of troponin-I, creatine kinase (CK), and CK-MB, all of which are biomarkers of myocarditis, were lower in Znrf1−/− mice." (PMID 37158982, 2023).
neuroblastoma (1 paper, 2024). Neuroblastoma (NB) is the most common solid, extracranial childhood tumor. "Interestingly, we observed the upregulation of Mgp and Mprip together with Znrf1 which is suggestive of neuronal differentiation, a key feature associated with a favorable clinical prognosis in neuroblastoma 21,22." (PMID 39668192, 2024).
non-small cell lung carcinoma (1 paper, 2021). A group of at least three distinct histological types of lung cancer, including non-small cell squamous cell carcinoma, adenocarcinoma, and large cell carcinoma. "To investigate the role of ZNRF1 in EGFR signaling, we depleted expression of the ZNRF1 gene in A549 non-small cell lung cancer cells by lentivirus-mediated small hairpin RNA (shRNA) transduction." (PMID 33996800, 2021).
Sepsis (1 paper, 2017). Sepsis is defined as life-threatening organ dysfunction caused by a dysregulated host response to infection. "In addition, we evaluated the effect of Znrf1 deficiency on septic shock using the CLP model, a clinically relevant rodent model of polymicrobial sepsis." (PMID 28593998, 2017). "In addition, mice with a myeloid-specific-deletion of ZNRF1 are significantly resistant to both LPS- and cecal ligation and puncture (CLP)-induced sepsis and exhibit a reduced inflammatory response, demonstrating the positive regulatory role of ZNRF1 in TLR4-driven inflammatory response." (PMID 28593998, 2017).
Splenomegaly (1 paper, 2026). Abnormal increased size of the spleen. "Myeloid-specific Znrf1 deletion caused age-dependent spontaneous splenomegaly and, upon allosensitization, elevated CD4+/CD8+ T-cell ratios, enlarged germinal centers with heightened IL-21/Tfh activity, and augmented alloantibody production." (PMID 41896526, 2026).
infection (3 papers, 2017 to 2021). The state of being infected such as from the introduction of a foreign agent such as serum, vaccine, antigenic substance or organism. "We assessed whether dysregulated EGFR signaling caused by ZNRF1 deficiency enhances HSV-1 entry during early infection." (PMID 33996800, 2021). "At 8 h post infection, ICP4 signals were significantly increased in ZNRF1–/– cells, indicating that loss of ZNRF1 increased HSV-1 infectivity." (PMID 33996800, 2021). "Furthermore, a higher viral load was detected in ZNRF1–/– cells infected with HSV-1 expressing GFP at 48 h post infection in comparison to wild type cells." (PMID 33996800, 2021). "Therefore, it may be worthwhile to investigate age-related defects in innate defenses against pathogen infection in association with the expression of CAV1 and ZNRF1." (PMID 28593998, 2017).
cancer (2 papers, 2021 to 2023). A tumor composed of atypical neoplastic, often pleomorphic cells that invade other tissues. "The ubiquitination of caveolin 1 (CAV1) mediated by zinc and ring finger 1 (ZNRF1) is blocked by circFARP1, thus leading to the release of leukemia inhibitory factor (LIF1) in cancer-associated fibroblasts (CAFs) and eventually promoting GEM resistance." (PMID 38174069, 2023). "In combination with ZNRF1 interference, which significant increases the infectivity of HSV-1, it may increase the efficacy of oncolytic virus therapy for the elimination of cancer." (PMID 33996800, 2021).
bacterial infection (1 paper, 2023). "Thus, although ZNRF deficiency renders cells resistant to EMCV and SARS-CoV-2 and mice to EMCV, mice with ZNRF1 deficiency are susceptible to bacterial infection due to increased lung tissue damage." (PMID 37158982, 2023).
ZNRF1 also shares sentences with these, for which no sentence is quoted: hepatocellular carcinoma (1 paper); lung carcinoma (1); neurodevelopmental disorder (1); pancreatic cancer (1); tumor (1).